BACC1 (BPTF associated chromatin complex component 1)
Description:
Component of chromatin complexes such as the MLL1/MLL and NURF complexes.
Synonyms: BAP18; C17orf49; MGC49942; HEPIS
Tractability: PROTAC: ubiquitination databases record sites on it.
Gene: Protein-coding gene on chromosome 17 (7,014,495 to 7,017,544, forward strand). Ensembl gene ENSG00000258315.
Subcellular location: Nucleus
Subcellular location (Human Protein Atlas): Nucleoplasm; Cytosol
Gene Ontology:
Molecular function: identical protein binding; protein binding
Cellular component: MLL1 complex; NURF complex; nucleus
Genetic constraint (gnomAD): Loss-of-function variants: 15 observed, 17.02 expected, observed/expected ratio (o/e) 0.88, 90% interval 0.59 to 1.36. The upper end of that interval is the gene's LOEUF score, 1.36, which puts it in group 5 of 6, group 1 being the genes least tolerant of losing a copy. Missense variants: 197 observed, 214.93 expected, observed/expected ratio (o/e) 0.92, 90% interval 0.81 to 1.03. Synonymous variants: 93 observed, 83.63 expected, observed/expected ratio (o/e) 1.11, 90% interval 0.94 to 1.32.
Homologues: Orthologues: macaque C16H17orf49 (99% identical), pig BACC1 (97% identical), chimpanzee C17H17orf49 (97% identical), dog BACC1 (95% identical), guinea pig BACC1 (95% identical), rat C10h17orf49 (95% identical), mouse Bacc1 (94% identical), rabbit BACC1 (93% identical), zebrafish BACC1 (74% identical), tropical clawed frog bacc1 (69% identical), zebrafish BACC1 (56% identical), Drosophila melanogaster CG33695 (44% identical), and 2 more.